MALAT1 (metastasis associated lung adenocarcinoma transcript 1)
Diseases named in the same sentence as MALAT1 in open-access papers (continued):
Sharing a sentence is not in itself a finding about the gene and the disease.
diabetic nephropathy (29 papers, 2017 to 2025). "For example, patients with diabetic nephropathy (DN) had a significantly higher expression level of circulating lncRNA Metastasis-associated lung adenocarcinoma transcript 1 (MALAT1), also known as NEAT2, which was accompanied by decreased levels of SOD." (PMID 37107272, 2023). "Research on molecular mechanism illustrated long noncoding RNA metastasis-associated lung adenocarcinoma transcript 1 (lncRNA MALAT1) mediated diabetic nephropathy by sponging miR-2355-3p/IL6ST axis." (PMID 35611768, 2022). "The long noncoding RNA metastasis-associated lung adenocarcinoma transcript 1 (MALAT1) are closely associated with the pathogenesis of diabetic nephropathy (DN)." (PMID 35910856, 2022). "LncRNA-metastasis-associated lung adenocarcinoma transcript 1 (MALAT1) has been implicated in the development of diabetic nephropathy through its epigenetic regulation of renal glomerular EC (HRGEC) gene expression." (PMID 34698214, 2021). "Binary regression analysis showed that ACR, creatinine, α1-MG, and LncRNA Malat1 were the risk factors for diabetic nephropathy with OR value of 1.166, 1.031, 1.031, and 2.019 (P < 0.05)." (PMID 32832561, 2020). "Therefore, it is of great interest to identify whether MALAT1 plays a role in diabetic nephropathy and high glucose‐associated podocyte damage." (PMID 28444861, 2017). "We previously demonstrated that circulating MALAT1 levels were increased in patients with diabetic kidney disease." (PMID 40978530, 2025). "In diabetic nephropathy, upregulation of Malat1 promotes renal fibrosis by targeting the miRNA-2355-3p, while in an experimental post-infarct myocardium mouse model, Malat1 mediates cardiac fibrosis by regulating TGF‐β1 activity via miRNA-145." (PMID 39363237, 2024). "In diabetic nephropathy (DN), deletion of MALAT1 restrained pyroptosis in high-glucose-treated HK-2 cells, suggesting the regulatory functions of MALAT1 in pyroptosis signaling pathway." (PMID 37013491, 2023). "Emerging evidence suggests that lncRNA MALAT1 is abnormally expressed in diabetic nephropathy (DN) and can attenuate renal fibrosis by modulating podocyte epithelial-mesenchymal transition (EMT)." (PMID 36760471, 2023). "Consistently, MALAT1 can positively regulate the level of transcription factor Krüppel-like factor 5 (KLF5) to enhance cellular damage in diabetic nephropathy." (PMID 36243708, 2022). "MALAT1 overexpression catalyzed pyroptosis in diabetic nephropathy to accelerate kidney impairment with the involvement of increased IL‐1β, IL‐18, Caspase-1, and GSDMD." (PMID 36243708, 2022). "MALAT1 enhanced diabetic nephropathy via suppression of miR-15b-5p and upregulation of TLR4 signaling." (PMID 36313695, 2022). "Consistently, MALAT1 was involved in high glucose-mediated podocyte injury in diabetic nephropathy via its interaction with β-catenin." (PMID 36313695, 2022). "MALAT1 aggravates renal tubular epithelial injury by interacting with LIN28A to activating the Nox4/AMPK/mTOR signaling in rats with diabetic nephropathy." (PMID 35813614, 2022). "It was demonstrated that MALAT1 was upregulated in patients with diabetic nephropathy and inversely correlated with the expression of klotho—a gene known to improve the function of hyperglycaemia (HG)-induced glomerular EC injury." (PMID 34698214, 2021). "In another study Malat1 was found to be increased in the cortex of mice with diabetic nephropathy as well as in cultured podocytes under high glucose conditions." (PMID 29467431, 2018). "In this study, we provided evidence that MALAT1 lncRNA was dysregulated in STZ‐induced diabetic nephropathy when proteinuria was marked and involved in high glucose‐induced podocyte damage." (PMID 28444861, 2017). "Finally, MALAT1 was notably highly expressed in kidney tissues from C57BL/6 mice with streptozocin induced diabetic kidney disease." (PMID 35058920, 2021).
diabetic nephropathy (continued). "Such research not only demonstrates the role of MALAT1 in devising the chromatin status of klotho but implies the prospect of targeting MALAT1 to ameliorate glomerular EC function in hyperglycaemia to impede the progression of diabetic nephropathy." (PMID 34698214, 2021). "Moreover, lncRNA MALAT1 modulates renal tubular epithelial pyroptosis in diabetic nephropathy via sponging miR-23c and targeting ELAVL1." (PMID 32370736, 2020). "In this study, we found that MALAT1 levels were increased in kidney cortices from C57BL/6 mice with streptozocin (STZ)‐induced diabetic nephropathy, and dynamically regulated in cultured mouse podocytes stimulated with high glucose, which showed a trend from rise to decline." (PMID 28444861, 2017). "Our in vivo data further identified a concomitant elevation of SRSF1 mRNA and MALAT1 in the kidney of STZ‐induced diabetic mice, suggesting MALAT1 and SRSF1, with associated disordered pre‐mRNA processing, contributed to the development and progression of diabetic nephropathy." (PMID 28444861, 2017). "MALAT1 activated LIN28 and Nox4/AMPK/mTOR pathway, resulting in promotion of renal tubular injury in diabetic nephropathy." (PMID 36313695, 2022). "MALAT1, LIN28A and Nox4 are upregulated in diabetic nephropathy tissues and high glucose-treated HK-2 cells." (PMID 35813614, 2022). "In this study, we established a mice model of diabetic nephropathy by STZ injection and assessed the levels of MALAT1 in kidney samples." (PMID 28444861, 2017). "QiHuangYiShen granules may inhibit the MALAT1 expression and Wnt/β-catenin pathway, contributed to the alleviation of renal fibrosis and attenuated the podocyte EMT in diabetic nephropathy." (PMID 39502508, 2024). "One study showed that podocyte injury could be due to abnormal MALAT1 expression and subsequent dysregulated let-7f and KLF5 in diabetic nephropathy." (PMID 36313695, 2022). "Among all the LncRNAs, LncRNA MALAT1 involves in regulating inflammation and NLRP3-mediated pyroptotic cell death in multiple diseases, including diabetic atherosclerosis, and diabetic nephropathy." (PMID 34503385, 2021). "Likewise, the circulating expression of MALAT1 is upregulated in patients with diabetic nephropathy, and there is a negative correlation between MALAT1 and the anti-oxidant enzyme, SOD." (PMID 35207562, 2022).
COVID-19 (28 papers, 2020 to 2025). A disease caused by infection with severe acute respiratory syndrome coronavirus 2. "MALAT1 has recently been implicated in T cell development and associated with COVID-19 immune response." (PMID 39613786, 2024). "Overall, our findings reveal that MALAT1 expression in T cells from COVID-19 patients is linked to a specific gene signature and that low MALAT1 expression is a hallmark of proliferative T cells." (PMID 36869729, 2023). "Numerous studies based on bioassays have identified changes in NEAT1 and MALAT1 expression in COVID-19 that have been associated with viral replication." (PMID 36852336, 2023). "Recent studies suggested that the upregulation of NEAT1 and MALAT1 may be associated with inflammation and consequent tissue damage seen in severe COVID-19." (PMID 38397917, 2024). "Low MALAT1 expression in cardiomyocytes can cause damage to the hearts of COVID-19 patients." (PMID 37109540, 2023). "The lncRNAs NEAT1 and MALAT1 are potential components of immune dysregulation in COVID-19 that may provide targets for severity related diagnostic measures or therapy." (PMID 33821282, 2021). "Thus, NEAT1 and MALAT1 are potential components of immune dysregulation in COVID-19 that may provide targets for severity related diagnostic measures or therapy." (PMID 35007307, 2022). "Studies on the role of MALAT1 in inflammatory lung injury in COVID-19 have shown that downregulation of MALAT1 facilitates inflammatory injury by inhibiting neutrophil chemotaxis and immune cell infiltration at the infected site." (PMID 36852336, 2023). "The downregulation of MALAT1 in patients with COVID-19 and the potential effects on cardiac health have been discussed." (PMID 37109540, 2023). "The first parameter MALAT1 (ENSG00000251562) was downregulated in this rule for the identification of patients with COVID-19." (PMID 37109540, 2023). "MALAT1 has been shown to be downregulated in severe COVID-19 patients and upregulated in mild COVID-19 patients in CD4+ T cells." (PMID 36950105, 2023). "We concentrated on CD8+ T cells due to their roles in COVID-19 pathology and the fact that MALAT1 expression co-varied with both proliferation and exhaustion markers in these cells." (PMID 36869729, 2023). "MALAT1 can be considered a reliable parameter for distinguishing patients with COVID-19 despite the fact that MALAT1 expression levels varied with the severity of COVID-19 and the type of cells tested." (PMID 37109540, 2023). "Focussing on the tissue, we used an independent patient cohort of post-mortem COVID-19 lung samples and demonstrated that MALAT1 suppression was indeed a marker of MKI67+ proliferating CD8+ T cells." (PMID 36869729, 2023). "COVID-19 is associated with proinflammatory cytokine release, suggesting that SARS-CoV-2 infection alters the expression of MALAT1." (PMID 37109540, 2023). "For example, MALAT1 was downregulated in proliferating T-cells from severe COVID-19 patients, while in another study, MALAT1 had a significantly lower overexpression level in the PBMCs from the severe group compared to the mild group." (PMID 38203577, 2023). "A long ncRNA, metastasis-associated lung adenocarcinoma transcript 1 (MALAT1), is upregulated in patients with cancer and various lung diseases, including COVID-19." (PMID 37814337, 2023). "We have discussed the basic function of the MALAT1 gene and its differential expression in patients with COVID-19." (PMID 37109540, 2023). "Similar results were also observed in saliva and nasopharyngeal swabs of COVID-19 patients, however, details of the mechanisms of MALAT1 upregulation and the cytokine production mediated by MALAT1 in COVID-19 have not been well illustrated." (PMID 35409008, 2022). "The lncRNAs NEAT1, MALAT1, and Tug1 are lncRNA-related therapeutic targets for the treatment of COVID-19 patients." (PMID 36204652, 2022).
COVID-19 (continued). "Very recently it has been shown that that NEAT1 and MALAT1 are highly expressed in saliva and nasopharyngeal swab samples of COVID-19 patients confirming the result in the present study." (PMID 34940755, 2021). "Changes to MALAT1 expression are a recurring observation in COVID-19 lncRNA profiling studies and infection models." (PMID 34564316, 2021). "Low levels of MALAT1 lncRNA were discovered in patients with severe COVID-19." (PMID 37109540, 2023). "However, the characteristics and mechanisms of action of NEAT1 and MALAT1 in COVID-19 are still unclear." (PMID 36852336, 2023). "Furthermore, both NEAT1 and MALAT1 have been recently connected to COVID-19 related inflammation, emphasizing a need for additional study of these lncRNAs." (PMID 35007307, 2022). "NEAT1 and MALAT1 are differential regulators of inflammation in severe COVID-19." (PMID 33821282, 2021). "This analysis also revealed several host-derived lncRNAs differentially expressed in COVID-19 patient-derived lung tissue, and in SARS-CoV-2 infected epithelial cells, including MALAT1 (metastasis-associated lung adenocarcinoma transcript 1) and NEAT1 (nuclear-enriched autosomal transcript 1)." (PMID 33129318, 2020). "For instance, metastasis-associated lung adenocarcinoma transcript 1 (MALAT1) and nuclear paraspeckle assembly transcript 1 (NEAT1) have been shown to be strongly associated with immune responses and possibly involved in the progression of the inflammatory process in COVID-19." (PMID 36852336, 2023). "Therefore, MALAT1 can be considered a potential feature for identifying patients with COVID-19." (PMID 37109540, 2023). "We indicated that the predicted lncRNA MALAT1-hsa-miR-124-3p/hsa-miR-30d-5p/hsa-miR-101-3p-EZH2 network may play a role in regulating ACE2 expression, whereas the lncRNA MALAT1-hsa-miR-92b-3p/hsa-miR-106b-3p/hsa-miR-25-3p-PTEN network may play a role in the inflammatory response to COVID-19." (PMID 36204652, 2022). "The downregulation of MALAT1 in our analysis could indicate a role for this lncRNA as an agent for the regulation of neutrophil chemotaxis that is rife in severe cases, in efforts to naturally alleviate inflammatory injury in COVID-19-positive cases." (PMID 33138195, 2020). "Using the gene expression omnibus (GEO) database Cantu et.al identified down-regulation of several skeletal muscle-related genes, including FOX01, Malat1, TIN and CXXC5 in patients with COVID-19." (PMID 39179952, 2025). "For example, lncRNA ROR1-AS1 and UGDH-AS1 have been reported to modulate immune response in the COVID-19 patients while NEAT1, MALAT1, and LINC00273 have been reported to modulate both immune and inflammatory response in severe COVID-19 patients." (PMID 38770134, 2024). "The MALAT1 anti-correlating gene signature shared by both CD4+ and CD8+ T-cells marked dividing T cells in both the lung and blood of COVID-19 patients." (PMID 36869729, 2023). "A growing body of evidence reveal that MALAT1 plays a significant role in lung diseases, such as asthma, COPD, COVID-19, IPF and PAH." (PMID 37250901, 2023). "The first parameter was MALAT1 (ENSG00000251562), which showed low expression levels in the cardiomyocytes of patients with COVID-19." (PMID 37109540, 2023). "Therefore, MALAT1 as a factor regulating neutrophil chemotaxis may be ubiquitous in severe cases, and its downregulation may play a role in alleviating inflammatory damage in patients with COVID-19." (PMID 36852336, 2023). "Performing RNAscope on COVID-19 post-mortem lung tissue from individuals who died of COVID-19, we confirmed that MKI67-expressing CD8+ T cells had lower levels of MALAT1 mRNA in situ." (PMID 36869729, 2023).
COVID-19 (continued). "According to previous studies, lncRNA MALAT1, lncRNA NEAT1, and lncRNA TUG1 were upregulated in COVID-19." (PMID 36204652, 2022). "MALAT1 and NEAT1, whose upregulation in SARS-CoV-2 infected cell lines and in BALF from COVID-19 patients was discussed earlier, also stand out in the comparative analysis of severe vs. non-severe cases." (PMID 36052163, 2022). "Four lncRNAs, MALAT1, NEAT1, TUG1 and GAS5 are predicted as potential therapeutic targets in COVID-19." (PMID 36204652, 2022). "In the COVID-19 BAL samples, CD4+ T cells overexpressed MALAT1 in mild patients and under-expressed it in severe cases." (PMID 34564316, 2021). "Gene signatures from three lncRNA gene markers (MALAT1, NEAT1, and SNHG25) were found to be downregulated in mild and severe cases of COVID-19, compared to normal controls." (PMID 33138195, 2020). "Further research into the roles of MALAT1 and NEAT1 in the context of COVID-19 will be valuable in further understanding the mechanism behind disease progression in the perusal of potential biomarkers and therapeutic intervention." (PMID 32646047, 2020). "Further downregulation of MALAT1 and NEAT1 was observed in mild-COVID-19 BAL cells, while SNHG25 was markedly downregulated in both mild- and severe-COVID-19 BAL cells." (PMID 33138195, 2020). "MALAT1, NEAT1, and SNHG25 long noncoding RNAs (lncRNAs) were downregulated in mild and severe COVID-19 BAL cells." (PMID 33138195, 2020). "In addition, multiple studies have shown that MALAT1 and NEAT1 are expressed differently in patients with COVID-19." (PMID 36852336, 2023). "In contrast to the previous discussion, the COVID-19-induced differential expression of MALAT1 in cardiomyocytes produced different negative effects on patients’ hearts." (PMID 37109540, 2023). "Thus, the high level of MALAT1, NEAT1 and EGOT observed in COVID-19 patients potentially work together and are correlated to the delayed IFN-I response." (PMID 36052163, 2022). "Finally, we predict the possible therapeutic targets of four lncRNAs, MALAT1, NEAT1, TUG1, and GAS5, in COVID-19." (PMID 36204652, 2022). "Previous studies have shown that lncRNA MALAT1 can regulate IL-6 and NLRP3 inflammatory cytokines, and lncRNA TUG1 plays an important role in the anti-inflammatory response to COVID-19 by blocking IL-6 cytokines." (PMID 36204652, 2022). "Lastly, our observation that CTSL, a protein crucial for COVID-19 viral entry is upregulated across multiple cell types in severe patients provides a potential initial mechanism for the induction of the NEAT1 and MALAT1 mediated inflammatory state through increased efficiency of viral entry." (PMID 35007307, 2022). "Additionally, MALAT1, NEAT1, and SNGH25 were downregulated in patients with mild and severe COVID-19." (PMID 33138195, 2020). "Thus, the precise role of MALAT1 and SOCS-1, whether as a potential therapeutic target of ALI/ARDS, a regulator of inflammation, or a biomarker in COVID-19, needs to be deciphered." (PMID 35807375, 2022). "Furthermore, the effects of MALAT1, NEAT1 and XIST are correlated with COVID-19 severity." (PMID 36052163, 2022). "Importantly, the role of PTEN gene in the ceRNA network predicted by lncRNA MALAT1 and lncRNA TUG1 may help in the discovery and clinical treatment of effective drugs for COVID-19." (PMID 36204652, 2022). "predicted lncRNA MALAT1 - hsa-miR-92b-3p/hsa-miR-106b-3p/hsa-miR-25-3p - PTEN and lncRNA TUG1 - hsa-miR-29a-3p/hsa-miR-29b-3p/hsa-miR-144-3p - PTEN networks may provide new targets for COVID-19 treatment and drug development, but the specific mechanism of action requires further study." (PMID 36204652, 2022).